XRCC1 (X-ray repair cross complementing 1)
Diseases named in the same sentence as XRCC1 in open-access papers (continued):
Sharing a sentence is not in itself a finding about the gene and the disease.
diabetes (6 papers, 2012 to 2026). "Xrcc1 repair gene polymorphisms are also positively associated with an increased predisposition to diabetes and its complications, adding to the evidence for defective repair genes in diabetes." (PMID 38001980, 2023). "After being adjusted for age, sex, smoking, drinking, diabetes, hypertension, and total cholesterol, logistic regression analysis indicated that XRCC1 rs25487 variant genotypes had significantly reduced IS risk (dominant model: OR = 0.53, 95% CI = 0.36–0.79, p = 0.002)." (PMID 27763529, 2016). "This study aimed to investigate the association between XRCC1 Arg399Gln and Arg194Trp single nucleotide polymorphisms (SNPs) and the risk and severity of polyneuropathy (DPN) in patients with type 2 diabetes mellitus (T2DM)." (PMID 41634070, 2026). "X-ray repair cross complementing 1 (XRCC1) is the major protein in the DNA BER system that is significantly reduced in patients with diabetes, whereas XRCC1 is significantly increased in diabetic patients treated with metformin." (PMID 35855344, 2022). "We analyzed potential interactions of rs1799782 and rs25487 in XRCC1 and rs1130409 in APE1 with known risk factors for PC, such as smoking, alcohol consumption, overweight, diabetes mellitus, and family history of PC." (PMID 22850545, 2012).
esophageal squamous cell carcinoma (5 papers, 2013 to 2020). Esophageal squamous cell carcinoma (ESCC) is a type of esophageal carcinoma (EC) that can affect any part of the esophagus, but is usually located in the upper or middle third. "The study of one Chinese population shows the strong association between XRCC1 Gln399Gln genotype and squamous-cell carcinoma of esophagus, and the smoking people have 4.2-fold increased risk in comparison with not smoking persons." (PMID 23675381, 2013). "The relative expression of XRCC1 was significantly lower in peripheral blood mononuclear cells from esophageal squamous cell carcinoma patients compared to the control group." (PMID 25800737, 2015). "The synergistic effects of JWA, XRCC1 and BRCA1 mRNA expression on personalized therapy remain unknown in advanced esophageal squamous cell carcinoma (ESCC)." (PMID 25925371, 2015).
ocular motor apraxia (5 papers, 2019 to 2025). "In humans, biallelic mutations in the XRCC1 gene are associated with neurodegenerative disorders, whose symptoms encompass ocular motor apraxia, axonal neuropathy, and progressive cerebellar ataxia." (PMID 35055077, 2022). "Furthermore, compound heterozygous mutations in human XRCC1 gene were shown to be responsible for ocular motor apraxia, axonal neuropathy and progressive cerebellar ataxia." (PMID 30991935, 2019).
oral mucositis (5 papers, 2013 to 2024). Inflammation of the mucous membranes of any of the structures in the mouth. "The XRCC1 rs25487 allele has been associated with severe oral mucositis in oropharyngeal carcinoma patients treated with radiotherapy." (PMID 35912186, 2022). "- XRCC-1 Arg194Trp polymorphism is significantly associated with oral mucositis (p = 0.01)." (PMID 38473311, 2024). "Furthermore, we analysed the linkage disequilibrium pattern for SNPs in XRCC1 and found that rs3213245, rs1799782, rs25489 and rs25487 were linked with severe oral mucositis while, rs1799782 and rs25489 were linked with severe skin reaction." (PMID 24594932, 2014). "In addition, genetic linkage disequilibrium existed in XRCC1 polymorphisms for >grade 2 oral mucositis and skin reaction indicating the complex inheritance pattern." (PMID 24594932, 2014). "Our results also showed that patients carrying with the XRCC1 (399Arg/Gln) genotype trended to have higher incidence of grade 3 oral mucositis." (PMID 23375119, 2013). "Our investigation shows, for the first time, that patients with the XRCC1 399Arg/Gln genotype were more likely to experience severe acute dermatitis and oral mucositis." (PMID 23375119, 2013). "In summary, our study illustrates, for the first time, that patients with the XRCC1 (399Arg/Gln) genotype were more likely to experience severe acute radiation-induced dermatitis and oral mucositis after radiation therapy." (PMID 23375119, 2013). "Regarding the effects of the polymorphism of XRCC1 on oral mucositis, there was no report about the association between XRCC1 (194Arg/Trp and 399Arg/Gln) genotypes and oral mucositis in the literature." (PMID 23375119, 2013). "Our analysis for XRCC1 haplotype did not associate with the risk of increased acute reactions, but NBN haplotype had an association for oral mucositis.." (PMID 24594932, 2014).
skin cancer (5 papers, 2004 to 2015). "In our present study, although our statistical analysis of each skin cancer and controls had potential biases, a significantly increased risk for skin cancer was associated with the SNP of XRCC1 Arg194Trp (AOR = 1.810, 95 % CI 1.03–318)." (PMID 22639094, 2012). "In our present study, the polymorphism of XRCC1 Arg194Trp has been shown to be an important factor in susceptibility to skin cancer among Japanese population." (PMID 22639094, 2012). "Two studies reported an association of risk in skin cancer with XRCC1 Arg194Trp, but the results were controversial." (PMID 22639094, 2012). "In the present study, we investigated the association between polymorphisms of XRCC1 and skin cancer in a Japanese population." (PMID 22639094, 2012). "The SNPs of XRCC1 has been associated with a risk factor of cancers such as lung cancer, breast cancer, prostate cancer, and also with skin cancers." (PMID 22639094, 2012). "We further investigated the gene–environment interactions between XRCC1 genetic variation and sun exposure-related risk factors on skin cancer risk." (PMID 15381933, 2004). "Although the number of each skin cancer has still been small, the polymorphisms of XRCC1 Arg194Trp could be involved in carcinogenesis of BCC and SCC." (PMID 22639094, 2012). "XRCC1’s contribution to repair of UV induced DNA damage might be affected by the diverging recruitment kinetics of the XRCC1 variants, and this could influence the risk of skin cancer." (PMID 23247283, 2012). "We investigated the XRCC1 gene polymorphisms of codon 194 and 399 in the each skin cancer." (PMID 22639094, 2012). "Our data suggest that the association of the XRCC1 Arg399Gln polymorphism with skin cancer risk may vary according to exposure dose and cancer type." (PMID 15381933, 2004). "We also observed a significant association of the carriage of XRCC1 194Trp allele with increased SCC risk, which was modified by a family history of skin cancer." (PMID 15381933, 2004). "On the other hand, in the case of AK and BD, XRCC1 Arg194Trp has no statistical significance, which indicates XRCC1 Arg194Trp would be related to susceptibility to not in situ but advanced skin cancer." (PMID 22639094, 2012).
adenoma (4 papers, 2006 to 2024). A neoplasm arising from the epithelium. "The XRCC1 280His allele was associated with an increased risk of adenomas with OR of 2.30 (95% CI 1.19–4.46) (OR 3.82, 95% CI 1.59–9.18 and OR 2.07, 95 % CI 1.05–4.10 for high- and low-risk adenomas, respectively)." (PMID 16542436, 2006). "The XRCC1 399Gln allele showed a trend towards risk reduction for carcinomas and adenomas, reaching statistical significance only for the high-risk adenomas, OR of 0.62 (95% CI 0.41–0.96)." (PMID 16542436, 2006). "In this study we identified an association between the XRCC1 280His allele and risk of colorectal adenomas and carcinomas, but again, this increased risk was only significant for the adenomas (OR 2.30, 95% CI 1.19–4.46)." (PMID 16542436, 2006). "The XRCC1 399Gln allele was associated with a reduction of risk of high-risk adenomas (OR 0.62, 95% CI 0.41–0.96)." (PMID 16542436, 2006). "The XRCC1 280His allele was associated with an increased risk of adenomas (OR 2.30, 95% CI 1.19–4.46)." (PMID 16542436, 2006). "In colorectal cancer samples, mutations of XRCC1 were significantly correlated with adenomas." (PMID 37679817, 2023). "Aberrant XRCC1 expression and mutations contribute to adenoma carcinogenesis." (PMID 37679817, 2023). "In our study, the XRCC1 399Gln allele was associated with a slightly decreased risk of colorectal adenomas and carcinomas, although statistically significant only for the high-risk adenomas, (OR 0.62, 95% CI 0.41–0.96)." (PMID 16542436, 2006). "The combination of the XRCC1 codon 280 and XRCC1 codon 399 polymorphisms showed a significant positive association for carriers of the XRCC1 codon 280 variant allele and XRCC1 codon 399 wild type allele, in the high-risk adenomas only, OR of 2.92 (95 % CI 1.20–7.10)." (PMID 16542436, 2006). "XRCC1 mutations occur in the precancerous stage of CRC and favor the progression from adenoma to carcinoma." (PMID 39195201, 2024). "No statistical significant associations were found between the haplotypes estimated in the XRCC1 gene and adenoma or carcinoma risk (further data not shown)." (PMID 16542436, 2006).
heart failure (4 papers, 2017 to 2023). Inability of the heart to pump blood at an adequate rate to meet tissue metabolic requirements. "In pressure overload‐induced heart failure, accumulation of single‐strand breaks was associated with more activated DNA damage response and deteriorated cardiac dysfunction in Xrcc1 deficient mutants." (PMID 36756698, 2023). "Our findings with Ercc1 deficiency are also consistent with a prior study demonstrating that deletion of Xrcc1, essential for repair of spontaneous, endogenous DNA singlestrand breaks, exacerbates heart failure in a mouse model of pressure overload‐induced heart failure." (PMID 36734200, 2023). "Cardiomyocyte-specific gene deletion of Xrcc1, an essential protein for SSB repair, leads to more severe cardiac inflammation and heart failure after pressure-overload, which is rescued by simultaneous deletion of Atm gene." (PMID 28436431, 2017).
lymph node metastasis (4 papers, 2017 to 2024). "In SC/ASC, XRCC1 positive expression was positively correlated with lymph node metastasis, invasion, and only receiving biopsy (all P < 0.05)." (PMID 32426369, 2020). "Our data demonstrated that XRCC1 positive expression was significantly related to lymph node metastasis, invasion, and poor prognosis, which was consistent with previous studies." (PMID 32426369, 2020). "Low XRCC1 expression was significantly correlated with lymph node metastasis and with worse overall and disease-specific survival in patients, as determined by log-rank tests." (PMID 29312615, 2017). "Two-tailed Fisher’s exact analysis revealed that XRCC1 expression in the carcinoma tissues of the training cohort clearly correlated with lymph node metastasis pN status (P=0.031)." (PMID 29312615, 2017).
oral cancer (4 papers, 2013 to 2023). "Nevertheless, in the stratified analyses based on cancer site, significant association was found between the XRCC1 Arg194Trp polymorphism and oral cancer under the allelic, heterozygote, and dominant models." (PMID 24497981, 2014). "A number of studies have reported the association between the XRCC1 Arg194Trp polymorphism and oral cancer risk." (PMID 24497981, 2014). "In our subgroup meta-analysis, we also detected the association of XRCC1 Arg194Trp with oral cancer risk." (PMID 24497981, 2014). "However, in stratified analyses based on cancer site, a significant association was found between the XRCC1 Arg194Trp polymorphism and oral cancer under the allelic, heterozygote, and dominant models." (PMID 24497981, 2014). "However, in the subgroup analyses of studies adjusted for smoking and alcohol, the XRCC1 Arg194Trp polymorphism was associated with increased risk of HNC and, in the stratified analyses based on cancer site, XRCC1 Arg194Trp was associated with increased risk of oral cancer." (PMID 24497981, 2014). "It has been reported that the XRCC1 Arg194Trp polymorphism may result in decreased repair efficiency of DNA damage, and the repair deficit may eventually increase an individual's susceptibility to oral cancer." (PMID 24497981, 2014).
osteosarcoma (4 papers, 2013 to 2022). A usually aggressive malignant bone-forming mesenchymal neoplasm, predominantly affecting adolescents and young adults. "High levels of spontaneous γH2AX foci were also detected in osteosarcoma U2OS cells depleted of FoxM1 by RNA interference, and correlated with decreased levels of X-ray repair cross-complementing protein 1 (XRCC1) and breast cancer–associated gene 2 (BRCA2), two genes involved in DNA repair." (PMID 23467617, 2013). "Acute high glucose exposure promoted XRCC1 expression through STAT3 activation, increasing the repair of methyl methanesulfonate-induced DNA damage in HEK293T cells and the osteosarcoma cell line U2OS." (PMID 35457130, 2022). "Acute high glucose (30 mM) exposures increased STAT3 activation and XRCC1 protein and gene expression in the non-tumorigenic HEK293T and osteosarcoma U2OS cell lines." (PMID 35457130, 2022).
Stroke (4 papers, 2006 to 2024). Sudden impairment of blood flow to a part of the brain due to occlusion or rupture of an artery to the brain. "Some of these studies include the association of the Arg399Gln (rs25487) polymorphism in the XRCC1 base excision repair (BER) gene with stroke and coronary atherosclerosis." (PMID 31214252, 2019). "In this study, polymorphisms of the DNA repair genes NEIL1 (rs4462560), NEIL3 (rs12645561) and XRCC1 (rs25487) were studied both as risk factors for the development of stroke and as modifiers of outcomes of ischemia." (PMID 27763529, 2016). "Two common polymorphisms, the C26304T (exon 6, Arg194Trp) and G28152A (exon 10, Arg399Gln) in the XRCC1 gene were studied both as risk factors for the development of stroke and as modifiers of the response of the brain to ischemia." (PMID 17087834, 2006). "Deficient DNA repair is closely associated with poor neurological outcomes after stroke, whereas upregulation of specific DNA repair enzymes such as APE1, OGG1, XRCC1, and Gadd45b can enhance long-term functional recovery after stroke." (PMID 39583099, 2024). "Our study suggests that independent of stroke etiology, there a major effect of the "T" allele of the C26304T polymorphism of the XRCC1 gene in the response of the brain to non lacunar ischemic stroke." (PMID 17087834, 2006).
Telangiectasia (4 papers, 2007 to 2021). Telangiectasias refer to small dilated blood vessels located near the surface of the skin or mucous membranes, measuring between 0.5 and 1 millimeter in diameter. "A boost and the XRCC1 (R399Q) polymorphism each contribute to the risk of telangiectasia, whereas an acute reaction and the TGFβ1(C-509T) polymorphism make independent contributions to the overall risk of fibrosis." (PMID 17325707, 2007). "The TGFβ1 (C-509T) polymorphism was significantly associated with an increased risk of fibrosis, whereas the XRCC1 (R399Q) polymorphism was significantly associated with an increased risk of telangiectasia." (PMID 17325707, 2007). "Fibrosis risk is associated with an inflammatory response (an acute reaction and/or TGFβ1), whereas telangiectasia is associated with vascular endothelial cell damage (boost and/or XRCC1)." (PMID 17325707, 2007). "In contrast, an additional 15 Gy electron boost and/or the inheritance of X-ray repair cross-complementing 1 (XRCC1) (R399Q) SNP contributed to the risk of telangiectasia." (PMID 17325707, 2007). "In addition, a 15 Gy electron boost and/or the inheritance of X-ray repair cross-complementing 1 (XRCC1) (R399Q) SNP contributed to the risk of telangiectasiae." (PMID 19603028, 2009). "The observed increased risk of telangiectasia in patients, who received an additional 15 Gy boost and/or are deficient in DNA repair owing to the inheritance of a variant XRCC1 (R399Q) allele, is consistent with the association of telangiectasia with vascular endothelial cell damage." (PMID 17325707, 2007). "As the 15 Gy boost also appears to increase the risk of telangiectasia, the XRCC1 (R399Q) association was performed excluding those patients who had received a boost (n=75) to determine whether the two risk factors were distinct." (PMID 17325707, 2007). "The XRCC1 Arg399Gln polymorphism has been reported to be associated with telangiectasia but not with fibrosis, particularly in patients who did not receive a boost, albeit based on 167 patients of whom 39 presented with telangiectasia." (PMID 19367277, 2009). "However, there are also dose-independent genetic risk factors as evidenced by the association of the XRCC1 (R399Q) DNA repair gene polymorphism with increased risk of telangiectases irrespective of the patient having received a boost." (PMID 34359812, 2021). "However, there are also dose-independent genetic risk factors as evidenced by the association of the XRCC1 (R399Q) DNA repair gene polymorphism with increased risk of telangiectasia irrespective of the patient having received a boost." (PMID 17325707, 2007).
acute myeloid leukemia (3 papers, 2014 to 2024). Acute myeloid leukemia (AML) is a group of neoplasms arising from precursor cells committed to the myeloid cell-line differentiation. "Here, we show that PARP inhibition using Olaparib perturbs BER in a XRCC1 dependent manner and causes synergistic lethality with 5-azadC in acute myeloid leukemia cell lines." (PMID 25074383, 2014). "Also, the XRCC1 polymorphisms have been extensively studied in relation to acute myeloid leukemia (AML), acute lymphoblastic leukemia, chronic lymphocytic leukemia, and lymphoma." (PMID 24955348, 2014).
anemia (3 papers, 2011 to 2024). A reduction in the number of red blood cells, the amount of hemoglobin, and/or the volume of packed red blood cells. "In a study of 285 NSCLC patients, XRCC1 rs25487 polymorphism showed significant associations with increased risk of grade 3-4 anemia, grade 3-4 neutropenia, grade 3-4 leukopenia and grade 3-4 thrombocytopenia." (PMID 39234108, 2024). "Univariate analyses for toxicity showed statistically significant associations between ERCC2 rs50872 (p = 0.03 in a recessive model) and XRCC1 rs25487 (p = 0.04 in a recessive model) and anemia." (PMID 39339159, 2024). "The same was true for ERCC1 8525C>T (leukopenia, P=1.000; neutropenia, P=0.909; anaemia, P=0.310; thrombocytopenia, P=0.625), and for XRCC1 variation (leukopenia, P=0.672; neutropenia, P=0.600; anaemia, P=0.158; thrombocytopenia, P=0.590)." (PMID 21364592, 2011).
breast tumors (3 papers, 2020 to 2023). "In a recent study, we have also shown that breast tumors that expressed low XRCC1 are also associated with high CD8+ TILs counts, aggressive phenotype and reduced poor survival." (PMID 38134458, 2023). "Herein, XRCC1 was predicted to have a significant genetic interaction with HRAS by network-based INCM co-mutation analysis of individual breast tumors (P = 8.45x10-3)." (PMID 32101536, 2020). "However, the prevalence of XRCC1 deficiency was ~15%, although XRCC1 deficiency was closer to 30% when breast tumors were BRCA1 deficient." (PMID 34067421, 2021). "Previously, we have shown that low RECQL breast tumors were significantly associated with low PARP1, BRCA1 negative, low RAD51, low ATM, low nuclear pChk1, low nuclear Chk2, low XRCC1, low FEN1, low SMUG1, and low DNA-PKcs expression." (PMID 38134458, 2023).